TNF (tumor necrosis factor)
Diseases named in the same sentence as TNF in open-access papers (continued):
Sharing a sentence is not in itself a finding about the gene and the disease.
Obesity (continued). "Also obesity is recognized as a state of chronic inflammation with increased circulating pro-inflammatory cytokines tumour necrosis factor (TNF)-α, interleukin (IL)-1β and IL-6." (PMID 36614882, 2022). "Moreover, TNF-α even can autoregulate positively its own biosynthesis in the adipose tissue, thus contributing to the maintenance of high TNF-α level in obesity." (PMID 35941819, 2022). "Patients with a sarcopenic obesity profile have a proinflammatory milieu (high levels of leptin, chemerin, and resistin, tumor necrosis factor (TNF)-α, interleukin (IL)-6, interferon (INF)-γ), and a decreased concentration of adiponectin and IL-15, which contributes to the progression of HCC." (PMID 36358709, 2022). "Individuals with obesity and depression evidence increased concentrations of peripheral and central inflammatory cytokines and acute phase reactants, such as interleukin (IL)-6, tumor necrosis factor alpha (TNF-α), and C-reactive protein (CRP) ⁠⁠." (PMID 35287577, 2022). "Abnormal secretion of cytokines (leptin, adiponectin, TNF-α, and IL-6) due to obesity may lead to insulin resistance in the body." (PMID 36079890, 2022). "Due to the clinical features of obesity and abdominal obesity, it may have higher levels of inflammatory cytokines and adipokines (eg, interleukin-1, interleukin-6, C-reactive protein, tumor necrosis factor alpha)." (PMID 35846319, 2022). "More importantly, miR-143 may be involved in the response of adipocytes to obesity-induced macrophage infiltration and cytokines secretion, as treatment of TNFα for 24 h to differentiated 3T3-L1 adipocytes reduced the expression of miR-143." (PMID 36430282, 2022). "Moreover, other research showed that the deletion of CerK suppresses obesity-related inflammatory cytokines IL-6 and TNFα and reduced macrophage infiltration in adipose tissue, resulting in reduced inflammatory responses in animals fed a high-fat diet." (PMID 35745168, 2022). "Furthermore, in a cafeteria diet-induced obese rat model, n-3 PUFA attenuated the symptoms of obesity-induced anxiety via exerting anti-inflammatory effects by decreasing IL-6 levels in the liver and TNF-α levels in the brain." (PMID 36358502, 2022). "Peripheral inflammation, mainly driven by IL-1β, TNF-α and IL-6, have been related to the disturbance of metabolic processes in individuals with schizophrenia (including insulin resistance, hepatic inflammation, and obesity)." (PMID 35625844, 2022). "Interestingly, there is compelling evidence illustrating that polycystic ovary syndrome (PCOS) patients affected by obesity exhibit high levels of TNF-α and IL-6 in serum and adipose tissues." (PMID 35747760, 2022). "Alternatively, obesity is associated with higher CRP via an increased mechanical load placed on joints, leading to ‘wear and tear’ and increased expression of the pro-inflammatory cytokines (e.g., IL-1β and TNF-α) which promote CRP production." (PMID 35301057, 2022). "Therefore, to our knowledge this is the first reported study showing evidence that TNF-α blockade with etanercept protects against endothelial dysfunction related with diet-induced obesity." (PMID 35206342, 2022). "The development of NAFLD is tightly tied to other clinical developments such as obesity, dyslipidemia, diabetes, and metabolic syndrome, associated with NAFLD extensively, such as PPAR, AMPK, PI3K-Akt, ER stress, TNF-α, and FAAs, and also associated with NAFLD progression." (PMID 35502176, 2022). "Research from our group showed that in obese Zucker rats, peritoneal macrophages present a local dysregulation in the constitutive or spontaneous release of pro-inflammatory cytokines such as IL-1β, INF-γ, IL-6, and TNF-α, contributing to the low-grade systemic pro-inflammatory state in obesity." (PMID 35276970, 2022).
Obesity (continued). "Aberrant TNF-α production and TNF receptor signaling have been associated with the pathogenesis of several diseases, including rheumatoid arthritis, Crohn’s disease, atherosclerosis, psoriasis, sepsis, diabetes, and obesity." (PMID 36501129, 2022). "It is also noted that the TNF-α level was increased under obesity conditions." (PMID 35354886, 2022). "In a rodent model of obesity, normalization of TNF-α decreased insulin resistance." (PMID 36292751, 2022). "Similarly, at the visceral adipose tissue level, HFD-induced obesity led to an up-regulation of the production of IL-1β, IL-6, TNF-α and MCP-1 as well as leptin and adiponectin." (PMID 35624723, 2022). "In obesity, the expansion of adipose tissue leads to chronic inflammation and hypoxia in the adipose tissue, and preadipocytes and adipocytes are often exposed to inflammatory cytokines such as interleukin (IL)-6 or tumor necrosis factor-alpha (TNF-α)." (PMID 35469126, 2022). "In the adipose tissue, TNF-α usually achieves high levels, and even though the exact mechanism leading to this increase is still unclear, positive biosynthesis autoregulation has been suggested, favoring the maintenance of elevated amounts in obesity." (PMID 35631100, 2022). "Obesity is a pro-inflammatory state that releases cytokines such as TNF-α and IL-6." (PMID 36568091, 2022). "TNF‐α secreted by adipose tissue is correlated with insulin resistance and the degree of obesity." (PMID 35154681, 2022). "In addition, due to the clear link between obesity and cataract caused by chronic inflammation and inflammatory markers such as CRP, IL-6 and TNF-α, and urinary isoprostanes, it is apparent that obesity is a risk factor contributing to cataract." (PMID 35565652, 2022). "In addition, elevated levels of p_Firmicutes are responsible for obesity and higher TNF-α levels in the population." (PMID 35958910, 2022). "Therefore, we performed TNF-α, IL-1β, and IL-6 mRNA expression analysis in the bone, in order to investigate the impact of D-gal-induced aging and obesity on bone inflammatory status." (PMID 35595806, 2022). "In OA combined with obesity, the subpatellar fat pad releases TNF-α, IL-6, IL-1, and IL-1β." (PMID 36439850, 2022). "Obesity-induced insulin resistance was found to be improved in TNF-α knockout mice, and elevated levels of TNF-α were observed to enhance the production of the pro-inflammatory factors MCP-1 and IL-6, as well as downregulating the expression of anti-inflammatory adipokines such as adiponectin." (PMID 35807921, 2022). "Obesity and high-fat diet are associated with the state of chronic systemic inflammation, which increases the levels of pro-inflammatory cytokines like IL1-β and tumor necrosis factor α (TNFα) by the adipose tissue." (PMID 35116217, 2022). "The TNF-signaling pathway is a critical crosslink between obesity and metaflammation." (PMID 36528638, 2022). "Adipose tissue inflammation, a hallmark of obesity and insulin resistance, contributes to aberrant lipolysis in an insulin-independent manner, particularly through the actions of TNFα and other inflammatory cytokines driving obesity-related adipose tissue inflammation." (PMID 35563078, 2022). "We previously reported that etanercept (an anti-TNF-α agent that binds to and functionally inactivates TNF-α) improved endothelial function in rats with diabetes mellitus, however, its effects on obesity-related vascular dysfunction remain unclear." (PMID 35206342, 2022). "Activation of the NF-κB and MAPK pathways in obesity occurs due to exposure to immune cells to increased circulating saturated fatty acids and LPS, increasing production of pro-inflammatory cytokines, including TNF-α and IL-6." (PMID 35215414, 2022).
Obesity (continued). "The classically activated macrophages (M1 macrophages) from the SVF have been recognized as the main source of proinflammatory cytokines in WATs, such as tumor necrosis factor α (TNF-α), interleukin-6 (IL-6) and interleukin-1β (IL-1β), and as key participants in obesity-induced inflammation." (PMID 35646489, 2022). "In addition, when IKK/NF-κB pathway is inhibited by pharmacological inhibitors of IKK2 salicylates and aspirin, the animal models show improved obesity-induced insulin resistance and reduced TNF-α production." (PMID 36230963, 2022). "This highlights the TNFα/NF-κB pathway in the MBH as a potential brain target for treating obesity." (PMID 33826123, 2022). "Another work reported that hypercaloric diets could induce obesity in partly due to microglia-hypersecretion of tumor-necrosis factor-α (TNFα) and mitochondrial dysfunction in the hypothalamic neurons." (PMID 39871928, 2022). "In the current study, etanercept treatment prevented body weight gain in CD-fed rats, supporting the idea that anti-TNF-α compounds could be useful as therapeutic agents to prevent diet-induced obesity." (PMID 35206342, 2022). "In addition, knockout of TNF-α or its receptor significantly enhanced insulin sensitivity and pharmacological inhibition of TNF-α attenuated obesity-induced insulin resistance." (PMID 35807921, 2022). "Obesity results in the increased secretion not only of TNF but also of resistin, IL1β and IL6." (PMID 36233290, 2022). "Besides macrophages, the inflammatory cytokines IL6 and TNF are additionally emitted from fat tissues and are known to be increased in obesity and insulin-resistant patients." (PMID 36432581, 2022). "With obesity, greater secretion of pro-inflammatory adipokines (including leptin, IL-6, TNF-α, and resistin) was observed, affecting satiety and lipid metabolism, along with a decrease in anti-inflammatory and insulin-sensitizing cytokines such as adiponectin and IL-10." (PMID 36364915, 2022). "Many adipocytokines, including TNF-α, Resistin and IL-6, positively correlate with obesity." (PMID 35565835, 2022). "Therefore, in the present work, the obesity condition was also evaluated in an in vitro model using human endometrial cells by adding TNFα to the cell cultures." (PMID 35409282, 2022). "We have reported that tumor necrosis factor (TNF)-related biomarkers, such as TNF receptors (TNFR1 and TNFR2) and progranulin (PGRN), are associated with the pathogenesis of obesity, diabetes, and CKD, and predict GFR loss and/or mortality in patients with diabetes and/or CKD." (PMID 36219652, 2022). "Compared with the NC group, the expression of IL-6 and TNF-α in hippocampal tissues of the mice from the OC group showed a significant increase (p < 0.05); on the contrary, swimming intervention reversed the obesity-induced increase of IL-6 and TNF-α (p < 0.05; p < 0.01)." (PMID 35745162, 2022). "Secondly, increasing circulating inflammatory cytokines induced by obesity, such as TNF-α, and higher leptin could lead to the inflammation and fibrosis in the liver." (PMID 36387941, 2022). "Moreover, in an in vivo study on mice fed a high-fat diet, it has been demonstrated that luteolin shows anti-obesity properties, decreases the body and epididymal fat weight and improves vascular dysfunction, by inhibiting the ROS and TNF-α action." (PMID 36616158, 2022). "In an obesity mice model fed a high-fat diet, TNF-α may impair mitochondrial biogenesis and function in different tissues of obese rodents, suggesting that fat accumulation in skeletal muscle may be caused by movement dysfunction and inflammation." (PMID 35634490, 2022). "Oxidative stress-induced senescence in adipose tissue is linked to higher leptin, IL-6, and TNF-α production in the SASP, suggesting that adipocyte senescence may be causal in obesity-related chronic inflammation." (PMID 36726470, 2022).
Obesity (continued). "Indeed, individuals with obesity and T2D had a lower production of IL-2 (proliferation marker), IL-6 and TNF-α by peripheral blood mononuclear cells (PBMCs) stimulated with phytohaemagglutinin, a T-cell mitogen." (PMID 35187037, 2022). "Human obesity, characterized by the expansion of adipose tissue, is considered a condition of a low-grade chronic inflammatory state characterized by the elevation of well-known inflammatory cytokines, such as TNFα and IL-6 within plasma." (PMID 35335277, 2022). "In addition, obesity has been recognized as proinflammatory state leading to elevated level of proinflammatory cytokines, such as TNF and interleukin (IL)-6, which favor the development of cancer." (PMID 35120118, 2022). "Furthermore, JXGTs inhibited obesity-induced inflammation by downregulating pro-inflammatory factors, such as IL-6 and TNFα." (PMID 35382381, 2022). "Obesity may increase bone resorption by upregulating pro‐inflammatory cytokines (IL‐6 and TNF‐α), which can stimulate osteoclast activity through the RANK pathway." (PMID 35304837, 2022). "Obesity could increase the levels of various growth factors, such as vascular endothelial growth factor, hepatocyte growth factor and tumor necrosis factor, creating a chronic inflammatory milieu that supports tumorigenesis." (PMID 35069893, 2022). "More importantly, the LI protocol improved insulin sensitivity, reduced fasting insulinemia, improve the level of the obesity-related adiponectin, decreased the level of the pro-inflammatory marker TNF-alpha and Il-6, and positively modulated the levels of exercise-induced myokines, irisin and BDNF." (PMID 35120179, 2022). "Obesity is associated with gradual adipose tissue infiltration with macrophages that secrete proinflammatory cytokines such as interleukin-6 (IL6) and tumor necrosis factor-α (TNFα)." (PMID 36364884, 2022). "Findings demonstrated that characteristics of systemic inflammation in obesity, including elevated pro-inflammatory cytokine production (TNF-α and IL-6) and upregulated NF-κB-related genes (NFKB1 and RELA), present in obesity were reduced by significant weight loss and ex vivo SCFA treatment." (PMID 35215414, 2022). "We found that the treatment with IAP preferentially inhibited the plasma levels of proinflammatory cytokines TNF-α and IL-6 compared to control colitis mice fed with diet-induced obesity, indicating the potent anti-inflammatory potential of this enzyme especially in obese mice." (PMID 35328382, 2022). "Moreover, the disorder of glucose metabolism regulation is one of the characteristics of obesity, and is often accompanied by elevated levels of chronic inflammatory markers in the liver and obese tissues, such as TNF-α, IL-6, and IL-1 β." (PMID 36232527, 2022). "Considering the inflammatory nature of obesity, where higher TNFα levels are secreted by adipose tissue, the efficacy of anti-TNF agents may be negatively affected." (PMID 36687448, 2022). "TNFα is increased in the adipose tissue of human and mice models of obesity and T2DM." (PMID 35684160, 2022). "These excess calories can cause chronic low-grade inflammation, as adipocyte hypertrophy in obesity results in increased infiltration of macrophages into adipose tissue, which secrete inflammatory cytokines, such as tumor necrosis factor-alpha (TNF-α) and interleukin 6 (IL-6)." (PMID 36364929, 2022). "Research on the combined effects of different SNPs on TNF-α levels and of the response of this important cytokine to intervention with dietary foods or products with anti-obesity and anti-inflammatory bioactivity is still in its infancy and requires further investigation." (PMID 36010524, 2022). "In addition, the enhanced production of proinflammatory cytokines TNF‐α and IL‐6 are key mediators of obesity‐mediated hepatocellular carcinoma." (PMID 35869934, 2022).
Obesity (continued). "In addition, WHR has been previously reported to be associated with inflammation markers, such as high-sensitivity C-reactive protein, TNF-α, amyloid A, and interleukine-6, in children affected by obesity-driven inflammation." (PMID 35806923, 2022). "Inflammatory cytokines such as TNF-α released from hypertrophic adipocytes and M1 macrophages infiltrating adipose tissues in obesity induce de novo ceramide synthesis from palmitate and transformation of sphingomyelin into ceramide by sphingomyelinase activity." (PMID 36003642, 2022). "Thus, along with IL-6, resistin, and TNF-α, leptin acts as an indicator of obesity initiation and insulin resistance." (PMID 36248900, 2022). "Obesity is caused by the accumulation of white adipose tissue (WAT), which functions as an energy reservoir and endocrine organ that secretes many adipokines such as leptin, resistin, adiponectin, and TNFα." (PMID 35478181, 2022). "This pathway is similar to that seen in obesity, including increased production of TNF-α and IL-6." (PMID 35962192, 2022). "Moreover, treatment of neuronal cells with the inflammatory molecules TNF-α and IL-6, which are also induced within the metabolic environment of obesity, activates syncytin-1 gene expression." (PMID 35444566, 2022). "Osteoporosis, obesity, and sarcopenia have been studied extensively as individual conditions, and strong evidence has been uncovered for the roles of inflammatory cytokines, such as IL-6, IL-1, and TNF-α, in their pathogenesis." (PMID 35764967, 2022). "Additionally, anthocyanins can reduce pro-inflammatory markers associated with obesity, such as CRP, IL-6, and TNF-α." (PMID 35740977, 2022). "After adjusting for sex, age, hypertension, blood lipid concentration, and obesity, the analysis of covariance revealed that the levels of IL-10, IL-4, and TNF-α in the case group were significantly higher than those in the control group (P < 0.001, P = 0.011, and P < 0.001, respectively)." (PMID 36160136, 2022). "A high-fat diet leads to a disturbance of lipid metabolism in the body with an abnormal increase in fatty acid content, inducing a significant inflammatory response in adipose tissue and secreting inflammatory markers such as tumor necrosis factor α into the body to further aggravate obesity." (PMID 36407552, 2022). "Later, obesity contributes to chronic inflammation via the stimulation of the nuclear factor-kappa B (NF-kB) pathway and produces inflammatory cytokines like interleukin (IL)-6 and tumor necrosis factor-alpha (TNF-α)." (PMID 36320966, 2022). "Leptin inhibits appetite and food intake, stimulates energy expenditure, and also has pro-inflammatory effects contributing to the low-grade chronic inflammation by enhancing the TNF-α and IL-6 production and vice versa TNF-α stimulated leptin secretion from adipocytes that induces obesity." (PMID 36297569, 2022). "Skeletal muscle oxidative stress induced by TNF-α is preventable by the administration of antioxidants, suggesting that TNF-α may provide an important target for confirming obesity-associated oxidative stress." (PMID 35216172, 2022). "TNF is illustrative of an adiposopathic link between obesity, metabolic disease, and cancer." (PMID 37990728, 2022). "Additionally, obesity triggers chronic inflammatory processes due to inflammatory cytokines, especially tumor necrosis factor-α (TNF-α), which induces the insulin resistance process." (PMID 35892791, 2022). "The aP2 gene also links obesity to insulin resistance by regulating the expression of TNF-α." (PMID 35163941, 2022). "Weight loss has been shown to improve inflammation in terms of several inflammatory markers associated with obesity, specifically decreases in pro-inflammatory biomarkers (CRP, TNF-α, IL-6, and leptin) and increases in the anti-inflammatory biomarker adiponectin." (PMID 35276970, 2022). "This way, an increase of salivary TNF-α, triggered by obesity, may contribute to the aggravation of oral inflammatory conditions." (PMID 35631100, 2022).